RNU6-738P (RNA, U6 small nuclear 738, pseudogene)
Gene: Small nuclear RNA gene on chromosome 5 (27,111,569 to 27,111,674, forward strand). Ensembl gene ENSG00000207261.
Homologues: Orthologues: chimpanzee U6 (97% identical), macaque U6 (93% identical), dog U6 (91% identical), rat U6 (85% identical). Paralogues in human: RNU6-1011P (92% identical), RNU6-12P (92% identical), RNU6-13P (92% identical), RNU6-26P (92% identical), RNU6-31P (92% identical), RNU6-32P (92% identical), RNU6-33P (92% identical), RNU6-1 (91% identical), RNU6-1060P (91% identical), RNU6-15P (91% identical), RNU6-17P (91% identical), RNU6-18P (91% identical), and 1285 more.